PLAU (plasminogen activator, urokinase)
Diseases named in the same sentence as PLAU in open-access papers (continued):
Sharing a sentence is not in itself a finding about the gene and the disease.
lung carcinoma (22 papers, 1998 to 2025). "Indeed, here we show that 70% of the inhibition of breast-to-lung cancer metastases is associated with the downregulation of expression of PLAU and CXCR4 in primary tumors in mice treated with BD." (PMID 22842551, 2012). "Since TM4SF1 has the ability to regulate Akt signaling and ARID1A loss leads to the activation of Akt signaling in lung cancer cells, we thus examined whether PLAU and TM4SF1 interaction is involved in the activation of Akt signaling in ARID1A-deficient lung cancer cells." (PMID 38229120, 2024). "NRF2 is considered a tumor suppressor, and HMOX1 its downstream effector to suppress lung cancer cells migration, via the transcriptional regulation of genes such as plasminogen activator urokinase (PLAU), MMP1, MMP9, and IGF binding protein-3 (IGFBP3)." (PMID 33537086, 2021). "PLAU and MMP12 have been reported to be associated with aberrant regulation of gene function and poor prognosis for lung carcinoma." (PMID 33072067, 2020). "Overexpression of IGFBP3 reduced migration and invasion by down-regulating PLAU in lung cancer cell lines H1299 and A54922." (PMID 31527696, 2019). "Combined our PPI network analysis with previous studies, PRAME knockdwon upregulates MMP1, CCL2, CTGF, and PLAU and contribute to lung cancer metastasis." (PMID 27391090, 2016). "In gene expression profiling studies of lung cancer cell lines to study therapeutic drug sensitivity, PLAU and CDH1 have been suggested as novel biomarkers of cetuximab sensitivity, and TGM2 was suggested as a potential marker of doxorubicin sensitivity." (PMID 20142997, 2010). "PLAU is upregulated in lung cancer and can promote lung cancer cell invasion." (PMID 38229120, 2024). "A decrease in PLAU expression was observed in four out of the five lung cancer cell lines." (PMID 36900323, 2023). "Furthermore, it has been reported that MMP1, HMGA2, TRPA1, and PLAU are highly expressed in various subtypes of lung cancer." (PMID 35354498, 2022). "Moreover, to silence PLAU led to a reduced capability of migration and invasion in lung cancer cell lines, H1299 and A54921." (PMID 31527696, 2019). "Similarly, PLAU plays a critical role in ECM degradation and has been linked to poor prognosis in several cancers, including head and neck squamous cell carcinoma (HNSCC) and lung cancer, through its role in promoting metastasis." (PMID 41465316, 2025). "A recent study reported that PLAU overexpression promotes progression in ESCC and tumors including breast, bladder, and lung cancer." (PMID 39149564, 2024). "Knockdown of PRAME decreases the expression of E-Cadherin and promotes the proliferation, invasion, and metastasis of lung cancer cells by regulating multiple critical genes, most of which are related to cell migration, including MMP1, CCL2, CTGF, and PLAU." (PMID 27391090, 2016). "Notably, elevated expression levels of production of immunoglobulin-related genes IGHG4, IGKC, IGLC2, IGHG3, and PLAU were detected in the SPP1-Mφ cluster, suggesting the proinflammatory and anti-tumor functions of this cluster in lung cancer." (PMID 36008393, 2022). "Moreover, PLAU and CXCR4 expression in primary tumors was significantly increased in animals with breast-to-lung cancer metastasis." (PMID 22842551, 2012). "Therefore, targeting PLAU and CXCR4 expression with natural compounds should result in the suppression of breast to lung cancer metastasis." (PMID 22842551, 2012). "Moreover, the relative expression of PLAU and CXCR4 in primary tumors is a predictive marker of breast-to-lung cancer metastasis because we have identified significant increase of these genes in animals with metastases." (PMID 22842551, 2012).
pancreatic cancer (21 papers, 2008 to 2025). "Inhibition of PLAU increases chemosensitivity of pancreatic cancer cells, which is associated with decreased stemness." (PMID 38229120, 2024). "Moreover, PLAU upregulation is negatively associated with these pathways, suggesting that downregulation of critical metabolic pathways in pancreatic cancer patients may result in worse outcomes." (PMID 36591282, 2022). "The bioinformatic analysis reveals that PLAU is induced in ARID1A-depleted pancreatic cancer, ovarian cancer, and esophageal cancer cells." (PMID 38229120, 2024). "The results demonstrated that CTSK and PLAU were overexpressed in pancreatic cancer and that the hypomethylation status of both genes was associated with a poor prognosis." (PMID 38077303, 2023). "Expression profiles and clinical data from the Cancer Genome Atlas (TCGA) were then used to compare the expression levels of CTSK and PLAU in pancreatic cancer and healthy pancreatic tissues via the Wilcoxon rank-sum test, with further validation using qPCR." (PMID 38077303, 2023). "Our findings contribute to the development of new therapeutic strategies for pancreatic cancer and lay the foundation for further studies to elucidate the role of PLAU and CTSK in this disease." (PMID 38077303, 2023). "Transwell assay showed that the migration and invasion abilities of PaTu8988 were stronger than those of BxPc3, suggesting that PLAU plays a great role in the migration and invasion of pancreatic cancer." (PMID 38077303, 2023). "Out of 11 ITGA3, MET, FNDC3B, PPP1R14B and KIAA0513, including PLAU, were previously reported as individual prognostic markers in the pancreatic cancer TCGA-PAAD cohort." (PMID 36591282, 2022). "In particular, in the PAAD cohort of pancreatic cancer, PLAU transcripts were 4.876 (p=1.6e-103) fold elevated compared with normal tissue." (PMID 36591282, 2022). "Identification of PLAU as hub gene in pancreatic cancer through screening multiple datasets has also been completed recently." (PMID 34093649, 2021). "The comparative toxicogenomics database was used to search for drug molecules that could target DSG3, MET, and PLAU in pancreatic tumors, obtaining 4, 26, and 39 drug molecules, respectively." (PMID 39513120, 2024). "It has been reported that CD40 and PLAU are involved in pancreatic cancer pathogenesis." (PMID 37024802, 2023). "Down-regulating PLAU or TOP2A can inhibit pancreatic cancer cell proliferation and migration." (PMID 36741321, 2023). "We verified the high expression of PLAU, LDHA, and PKM in pancreatic cancer cells using qPCR in vitro, and we also discovered that the expression of PLAU, LDHA, and PKM in hypoxic pancreatic cancer cells differed from that in normal cultured pancreatic cancer cells." (PMID 37277450, 2023). "To summarize, our findings suggest that CTSK and PLAU may serve as novel potential biomarkers for pancreatic cancer." (PMID 38077303, 2023). "In pancreatic cancer, existing studies have shown that PLAU may be related to lymphatic metastasis, but its specific molecular mechanism is yet to be elucidated." (PMID 38077303, 2023). "Importantly, we have validated the concept of a key role for PLAU/uPA in cancer progression and its potential as a therapeutic target by performing studies in an orthotopic pancreatic tumour model." (PMID 36591282, 2022). "Of particular relevance to this study, pancreatic cancer and cell lines, consistently demonstrate upregulation of PLAU gene expression, suggesting that PLAU may play driver roles in the development and progression of PDAC." (PMID 36591282, 2022). "Moreover, PLAU was also reported to be involved in the pharmacology of triptolide to alleviate proliferation and migration of pancreatic cancer cells." (PMID 34244472, 2021). "Consequently, CTSK and PLAU have potential as prognostic biomarkers for pancreatic cancer." (PMID 38077303, 2023).
pancreatic cancer (continued). "Moreover, since upregulation of PLAU levels is also frequently observed in a number of malignancies and upregulation of PLAU is a prognostic marker not only in pancreatic cancer but also in head and neck, endometrial cancer, renal and lung, breast and oesophageal cancer." (PMID 36591282, 2022). "For the treatment of pancreatic cancer, triptolide at the dose of 10–40 nM could inhibit pancreatic cancer cell proliferation through the suppression of hedgehog signaling pathway, or via the inhibition of plasminogen activator urokinase (PLAU)." (PMID 36408249, 2022). "In conclusion, our study identified PLAU and CTSK as potential biomarkers for pancreatic cancer through bioinformatics analysis of microarray data." (PMID 38077303, 2023). "The results showed that COL1A1, PLAU, and CTSK were highly expressed in the three datasets, with COL1A1 having been shown to play a significant role in pancreatic cancer." (PMID 38077303, 2023). "The expression of PLAU and CTSK was significantly higher in pancreatic cancer samples than in normal breast tissues (p < 0.001)." (PMID 38077303, 2023). "Pancancer analysis suggested that PLAU and CTSK were differentially expressed in pancreatic cancer and other cancers such as kidney chromophobe, stomach adenocarcinoma, and v = ovarian serous cystadenocarcinoma." (PMID 38077303, 2023). "On the other hand, PLAU interacted directly with one negatively correlated gene, ANG (angiogenin), the high expression of which is reported to be favourable in pancreatic cancer." (PMID 36591282, 2022). "This study is aimed at employing bioinformatics to investigate and comprehend the expression of PLAU and CTSK in pancreatic cancer, as well as their relationship with clinicopathological and prognostic significance, underlying molecular mechanisms, and immune cell infiltration, to aid physicians." (PMID 38077303, 2023). "We identified PLAU, LDHA, and PKM as key genes involved in pancreatic cancer hypoxia through GO/KEGG enrichment related hypoxia pathways and cox regression, established prognostic models, and studied their relationship to immune invasion through bioinformatics using R and related online databases." (PMID 37277450, 2023). "By integrated analysis of our data and publicly available bioinformatics resources, we found that a combination panel consisting of CDH3, PLAU, and LFNG might improve the prognosis of overall pancreatic cancer survival." (PMID 27869176, 2016). "As the molecular mechanism of CTSK and PLAU in the development of pancreatic cancer has not been studied, we identified the DEGs of these two genes in pancreatic cancer through the DsEq2 package and conducted functional studies of KEGG, GO, and GSEA enrichment." (PMID 38077303, 2023).
gastric cancer (20 papers, 2007 to 2024). A primary or metastatic malignant neoplasm involving the stomach. "Previously, we found that overexpression of FOXM1 and PLAU were associated with gastric cancer progression and poor prognosis." (PMID 31949481, 2020). "Kaplan-Meier curve analysis using pooled gastric cancer dataset indicate that FOXM1+PLAU+ subgroup predict the worst prognosis, while FOXM1-PLAU- subgroup have the best OS and RFS." (PMID 31949481, 2020). "In gastric cancer, PLAU could act together with its co-expression gene to predict a worse survival status." (PMID 34093649, 2021). "As a conclusion, the predicted inhibitors which could reverse the gene expression pattern in the different FOXM1/PLAU status groups may serve as potential therapeutic options in the gastric cancer in the future." (PMID 31949481, 2020). "Therefore, those predicted inhibitors which could reverse the gene expression patterns of the FOXM1+PLAU+ subgroup may worth exploring as new therapeutic options for gastric cancer." (PMID 31949481, 2020). "Thus, FOXM1 and PLAU may function coordinately to promote gastric cancer progression and therapeutic resistance through multiple signaling pathways." (PMID 31949481, 2020). "A state-of-art work indicated that PLAU, which is overexpressed in tumor tissues, functioned collaboratively with FOXM1 in the promotion of gastric cancer progression." (PMID 34244472, 2021). "PLAU and CTSK have been shown to play a role in various tumors, with PLAU being considered as a potential biomarker in head and neck squamous cell carcinoma, promoting the EMT process, and tumor development in gastric cancer by cooperating with FOXM1." (PMID 38077303, 2023). "As mentioned, FOXM1 and PLAU are indicators of poor prognosis with shorter OS and RFS time in the gastric cancer, and results from microarray also indicated FOXM1+PLAU+ related genes are enriched in TGF-beta, DNA repair, MAPK and drug resistance signaling pathways." (PMID 31949481, 2020). "The potential therapy capacity of FOXM1 and PLAU is not limited in the gastric cancer, also suitable for the NSCLC." (PMID 31949481, 2020). "The PLAU (plasminogen activator urokinase) protein has been shown to mediate the Treg suppressor function via STAT5 and ERK signaling pathways and could provide certain help for future treatment in gastric cancer together with FOXM1." (PMID 33718118, 2020).
colorectal cancer (17 papers, 1989 to 2025). A primary or metastatic malignant neoplasm that affects the colon or rectum. "This PLAU variant has previously been associated with an increased risk of colorectal cancer, asthma, oral tongue squamous cell carcinoma, and poor coronary collateral circulation in coronary artery disease patients, as well as Alzheimer’s Disease39,46–49." (PMID 34079037, 2021). "Moreover, downregulation of miR-193a-3p in IBD is related with the promotion of colitis-associated colorectal cancer acting on the target mRNAs of the Interleukin-17 receptor D (IL-17RD) and the plasminogen activator urokinase (PLAU)." (PMID 39203856, 2024). "PLAU is involved in tumor cell migration and invasion in pancreatic ductal adenocarcinoma and colorectal cancer." (PMID 35912229, 2022). "Overexpression of PLAU significantly promoted the proliferation, migration and angiogenic abilities of colorectal cancer cells." (PMID 35141223, 2022). "Suppression of PLAU by miR-193a-3p was also identified as a mechanism that inhibits the development and progression of colorectal cancer." (PMID 34244472, 2021). "In addition, PLAU, sometimes referred to as a urokinase-type plasminogen activator (uPA), stimulates the movement, infiltration, and multiplication of colorectal cancer cells through the Src/ERK pathway." (PMID 38970097, 2024). "FABP6, hypermethylated SFRP1, XDH, PLAU, ADH1C, HSD17B2, and SPP1 have been identified more as a colorectal cancer biomarker than as a therapeutic target at present." (PMID 34381520, 2021). "In colorectal cancer (CRC), METTL3 upregulates plasminogen activator urokinase (PLAU) mRNA in a m6A-dependent manner and participates in the mitogen-activated protein kinase (MAPK)/extracellular signal-regulated kinase (ERK) pathway to promote tumor angiogenesis and metastasis." (PMID 39295872, 2024).
glioma (14 papers, 2009 to 2025). A benign or malignant brain and spinal cord tumor that arises from glial cells (astrocytes, oligodendrocytes, ependymal cells). "A study has reported that aberrant PLAU expression is associated with glioma progression and poor prognosis in patients with glioma." (PMID 40143204, 2025). "Abnormal expression of PLAU is associated with the development of glioma and the prognosis of glioma patients." (PMID 37759283, 2023). "Some previous studies have also shown that up-expression of PLAU was associated with glioma growth, invasion, and angiogenesis." (PMID 37298284, 2023). "This study aims to evaluate the prognostic value of PLAU/PLAUR transcription expression in glioma and to explore how these pairs of genes affect the generation and progression of glioma." (PMID 35087738, 2021). "In conclusion, our current study indicated that overexpression of PLAU and PLAUR is associated with poor prognosis in primary and recurrent glioma patients, especially in LGG." (PMID 35087738, 2021). "Upregulation of PLAU also promotes the migration of glioma cells." (PMID 37759283, 2023). "High expression of PLAU predicted poor prognosis in regard of all gliomas." (PMID 35087738, 2021). "High mRNA expression of PLAU (HR=1.578, 95%CI 1.208-2.061, p=0.0008) and PLAUR(HR=1.38, 95%CI 1.05-1.814, p=0.0211) were independently associated with significantly shorter OS of glioma patients." (PMID 35087738, 2021). "Oncomine database was applied to investigate whether there were differences between glioma and normal brain tissue in the expression of the PLAU gene." (PMID 35087738, 2021). "First, the transcription expression level of PLAU/PLAUR among glioma patients were investigated." (PMID 35087738, 2021). "Furthermore, Overexpression of PLAU can largely rescue self-renewal, migration, invasion and vascular formation defects of repressed glioma cells." (PMID 29340066, 2017). "Moreover, Gene co-expression network analysis enlightens us that immune therapy and specific cancer-related signaling pathway blocking by targeting PLAU/PLAUR might be a new idea for treating glioma." (PMID 35087738, 2021). "Multiple studies have shown that PLAU and PLAUR are highly expressed in gliomas and promote glioma cell invasion, tumor growth, and angiogenesis." (PMID 40224547, 2025). "PLAU and PLAUR transcriptional expressions are found significantly higher in glioma compared with normal brain tissue, and are more obvious in high-grade gliomas." (PMID 35087738, 2021). "High expression of PLAU and PLAUR predicted a poor prognosis in primary glioma and recurrent glioma patients, especially in lower grade gliomas." (PMID 35087738, 2021). "Significant changes of PLAU and PLAUR expression in transcription level between glioma and normal brain tissues (ONCOMINE)." (PMID 35087738, 2021). "TRIM38, CCR5, PLAU, P2RY8, and PROS1 were upregulated in glioma tissues, while HAMP and S100A9 were downregulated." (PMID 34954691, 2021). "Transcription levels of PLAU and PLAUR were evidently higher in GBM and lower-grade glioma (LGG) than in normal brain tissues." (PMID 35087738, 2021). "Overexpression of PLAU and PLAUR is regarded as independent prognostic factors for shorter OS of glioma patients through Cox regression analysis." (PMID 35087738, 2021). "Fifth, it is hard to know how PLAU and PLAUR expression can be involved in the glioma formation, or their expression is a consequence of the glioma development." (PMID 35087738, 2021). "This study aims to evaluate the prognostic value of PLAU/PLAUR transcription expression in glioma and to explore how they affect the generation and progression of glioma." (PMID 35087738, 2021). "We observed that the IRSs of PROS1, P2RY8, PLAU, CHI3L2, MSR1, CCR5, and TRIM38 were higher than its corresponding IRSs in low-grade glioma, while the IRSs of HAMP, CARD16, and S100A8 in high-grade glioma were lower than low-grade glioma." (PMID 34954691, 2021).